CTAGE15 (CTAGE family member 15)
Synonyms: CTAGE15P; cTAGE-15
Tractability: Antibody: UniProt predicts a signal peptide or a membrane-spanning region.
Gene: Protein-coding gene on chromosome 7 (143,571,801 to 143,574,387, forward strand). Ensembl gene ENSG00000271079.
Subcellular location: Membrane
Gene Ontology:
Biological process: endoplasmic reticulum to Golgi vesicle-mediated transport; protein secretion; vesicle cargo loading
Cellular component: endoplasmic reticulum exit site; endoplasmic reticulum membrane; membrane
Genetic constraint (gnomAD): Loss-of-function variants: 0 observed, 4.27 expected, observed/expected ratio (o/e) 0, 90% interval 0 to 0.7. That is too few expected variants to judge how well the gene tolerates losing a copy. Missense variants: 21 observed, 44.73 expected, observed/expected ratio (o/e) 0.47, 90% interval 0.33 to 0.68. Synonymous variants: 3 observed, 15.36 expected, observed/expected ratio (o/e) 0.2, 90% interval 0.088 to 0.5.
Homologues: Orthologues: dog MIA2 (76% identical), mouse Mia2 (68% identical), rat Mia2 (68% identical), Drosophila melanogaster Tango1 (21% identical). Paralogues in human: CTAGE6 (99% identical), CTAGE8 (97% identical), CTAGE4 (97% identical), CTAGE9 (96% identical), MIA2 (83% identical), CTAGE1 (75% identical), MIA3 (26% identical), SPZ1 (8% identical), MIA (2% identical), OTOR (1% identical).
Diseases named in the same sentence as CTAGE15 in open-access papers:
CTAGE15 is named in the same sentence as 1 disease in open-access papers, as found by Europe PMC text mining. Sharing a sentence is not in itself a finding about the gene and the disease. The quoted sentences say what the papers report.
tumor (1 paper, 2016). "The array data showed that 16 of the 18 selected DMRs were hypermethylated and two regions, FRG1BP and CTAGE15, were hypomethylated in primary tumors compared to tumor-adjacent normal lung tissue." (PMID 27782156, 2016).